TNF (tumor necrosis factor)
Diseases named in the same sentence as TNF in open-access papers (continued):
Sharing a sentence is not in itself a finding about the gene and the disease.
neurodegenerative disease (continued). "In pathological conditions, microglia release large amounts of TNF-α and scientific evidence has identified TNF-α involvement in the pathogenesis of neurodegenerative disease." (PMID 30336612, 2018). "These inflammatory mediators, such as TNF-α, IL-1ß, IL-6 and PGE2, play an important role in the pathological process of neurodegenerative diseases." (PMID 28410218, 2017). "This non-resolving pattern of inflammation in the brain is consistent with the consequences of injecting LPS, the prototype TNF inducer, and a TLR4 agonist, in order to generate models of neurodegenerative disease in rodents." (PMID 28451786, 2017). "Therefore, TNF-α is a key cytokine of the immune system that initiates and promotes neuroinflammation, which under uncontrolled conditions may lead to the development of neurodegenerative diseases." (PMID 27075886, 2016). "Another TNF construct referred to as TNFR2-specific sc-TNF variant has been shown to rescue human neurons from cell death highlighting the potential application of TNF analogues, especially with preferential TNFR2 agonism in neurodegenerative diseases." (PMID 26266038, 2015). "This suggests that TNFα exerts its neuroprotective function by maintaining BBB permeability and suppressing infiltration of M1 monocytes in neurodegenerative diseases." (PMID 26465009, 2015). "Increasing evidence has demonstrated that microglial activation and the consequent release of proinflammatory and cytotoxic factors such as TNFα, IL-1β, NO, and prostaglandin E synthase 2 (PGE2) are thought to contribute to the neurodegenerative diseases." (PMID 24349614, 2013). "The cytokine tumor necrosis factor-alpha (TNF-α) is a major mediator of inflammation that is commonly upregulated in biological samples from patients and animal models of human neurodegenerative disease." (PMID 22642825, 2012). "Thus, COX-2, iNOS and MMP-9 activities, as well as TNFα, IL-1β and NO generation have become accepted as markers and therapeutic targets in neurodegenerative diseases, and thus their down-regulation might assist in preventing or delaying the onset of these diseases." (PMID 22018032, 2011). "The elevated levels of TNF-α and IL-6 observed in LDDD patients align with previous findings that underscore the role of these cytokines in promoting inflammation, matrix degradation, and pain in degenerative diseases." (PMID 40095903, 2025). "This is not surprising, given that TNF-α contributes to the development and progression of neurodegenerative diseases, by activating inflammatory and apoptotic signaling pathways, which exacerbates disease progression and neuronal loss." (PMID 40038202, 2025). "Furthermore, increased expression of proinflammatory cytokines such as IL-6, IL-1β, and TNFα that we detected in IFNγ treated SPG11 iMGL, was also described for iPSC-derived microglia from patients with other neurodegenerative diseases, including PD and ALS." (PMID 38305941, 2024). "The BBB is responsible for protecting the central nervous system (CNS) from the peripheral immune system; however, in many neurodegenerative diseases, such as AD, the integrity of the BBB is compromised by cytokines released by inflammation in the CNS, including TNF-α, IL-6, and IL-1β." (PMID 37323140, 2023). "Thalidomide belongs to a class of drugs that target the 3′-untranslated region (UTR) of tumor necrosis factor alpha (TNF-α) mRNA, inhibiting TNF-α production, and have multipotent and pleiotropic effects, thus being tested to treat neuroinflammation in neurodegenerative diseases." (PMID 38047750, 2023). "Given the role of TNFα in immune and inflammatory activity, this is not surprising, considering an innate immune response is characteristic of neurodegenerative diseases like ALS." (PMID 38260713, 2023).
neurodegenerative disease (continued). "Astrocytes may contribute to inflammation by serving as an inducible source of inflammatory cytokines, such as IL1β, TNFα, and IL6; these cytokines have been demonstrated to be involved in neurodegenerative diseases, including ALS pathogenesis." (PMID 36046683, 2022). "Particular care must also be emphasized regarding anti-TNF-alpha therapy for patients whose family medical history shows the incidence of neurodegenerative diseases due to a lack of certainty as far as the mechanism of development of these complications." (PMID 35054511, 2022). "Investigating the anti-TNF agents has been growing as the subject of interest in the treatment of neurodegenerative diseases; however, some have shown no beneficial effects." (PMID 35651608, 2022). "High expression of several proinflammatory cytokines and chemokines, including TNF-alpha, MCP, IL-6, and IL-1, have been found in brain tissues from autopsies of patients with neurodegenerative diseases such as PD and MSA, suggesting that these cytokines are involved in the progression of MSA." (PMID 34900026, 2021). "We chose to measure changes in the mRNA expression of interleukin-1β (IL-1β), tumor necrosis factor-α (TNF-α), Fas, interleukin-6 (IL-6), leukemia inhibitory factor (LIF), and interferon γ (IFN-γ) based on their potential involvement in neurodegenerative diseases." (PMID 33628191, 2021). "The function of ADAM17 in neurodegenerative diseases has not been fully elucidated yet because of a lack of suitable knockout mice; thus, we can predict its role based on in vivo investigations of TNF in neuroinflammation." (PMID 33579029, 2021). "Activated microglia can produce inflammatory cytokines, including tumor necrosis factor-alpha (TNF-α), interleukin-1β (IL-1β), and reactive oxygen species (ROS), which could result in the progression of neurodegenerative diseases." (PMID 33362467, 2020). "Thus, in a scenario with high levels of TNFα and low levels of FAIM as reported in some neurodegenerative diseases, TNFα signaling can be switched from a pro-survival to a pro-apoptotic response." (PMID 33425889, 2020). "Here, we critically review the relationship between αS and microglial activation depending on its aggregation state and its role in neuroinflammation to explore the potential of TNFα inhibitors as a treatment strategy for MSA and other neurodegenerative diseases." (PMID 30975183, 2019). "Cytokines, including TNF-α and IL-1β, have been shown to mediate reactive astrogliosis, which is reflected by the expression of glial fibrillary acidic protein (GFAP) and cell migration, in neurodegenerative diseases." (PMID 31185608, 2019). "These inflammatory mediators, such as tumor necrosis factor-α (TNF-α), interleukin (IL) -6, IL-1β, glutamate, nitric oxide, and reactive oxygen species, can collectively lead to neuronal damage, resulting in the progress of neurodegenerative diseases." (PMID 27075756, 2016). "The inflammatory mediators, such as interleukin-1β (IL-1β), interleukin-6 (IL-6), tumor necrosis factor-α (TNF-α), chemokines and oxygen free radicals are assumed to stimulate signaling pathways in a pathological cascade to result in neurodegenerative diseases." (PMID 22607609, 2012). "We speculated that TNF-α may not induce the onset and progression of neurodegenerative diseases by acting on the orexin system." (PMID 35250828, 2022). "Strength training for 6-12 weeks did not alter plasma IL-1β, IL-2, IL-6 and TNF-α concentration in healthy elderly adults and patients with chronic-degenerative diseases, while 12 weeks of resistance training decreased muscle TNF-α mRNA in frail elderly individuals." (PMID 33936044, 2021). "Even the increase of TNFα observed after mLPS and MPTP administration lowered to levels similar to control mice without minocycline treatment, indicating that microglial source of TNFα may play a crucial role in the development of neurodegenerative diseases." (PMID 32015787, 2020).
neurodegenerative disease (continued). "This is reasonable that the alterations of TNF-α levels in ALS may be not specific in neurodegenerative diseases, and most disease control subjects in this meta-analysis were neurological disease." (PMID 28831083, 2017). "Therefore, the level of TNF-α is a key step in neurodegenerative diseases and inhibition of TNF-α production from microglia may be an effective strategy against the neuronal damage mediated by TNF-α." (PMID 29358962, 2017). "However, this TNF-glutaminase link, despite first being made a decade ago (above), does not yet appear to be common currency in neurodegenerative disease circles." (PMID 27596607, 2016). "This review summarizes the current knowledge of the cellular and molecular mechanisms by which TNF-α potentiates excitotoxicity and describes its key role in linking the neuroinflammatory and excitotoxic processes that take place not only in ALS but also in other common neurodegenerative diseases." (PMID 24966471, 2014). "Moreover, choline has shown neuroprotective effects in the brain and neurodegenerative diseases; therefore, in the current study, the protective role of choline was evaluated after pre-incubation of NSC-34 cell lines with inflammatory cytokines (LPS, TNF-α, and H2O2)." (PMID 36365192, 2022). "PINCH is increased in other neurodegenerative diseases besides HIV, making it clear that Tat is not the only factor for the induction of PINCH, but rather likely works in part through induction of TNFα." (PMID 32746944, 2020). "TNF-α administration also reduces the peroxisome proliferator-activated receptor (PPAR)-γ co-activator 1α (PGC-1α) in myoblasts and human cardiomyocytes even though the effect of TNF-α on neuronal cells of various neurodegenerative diseases has not yet been reported." (PMID 32455946, 2020).
metabolic disorders (397 papers, 2007 to 2026). "Tumor necrosis factor α (TNFα) regulates inflammation in metabolic diseases and probably aging-associated inflammation." (PMID 41530146, 2026). "The buildup of abdominal fat promotes the release of adipokines, such as TNF-α and IL-6, activating signaling pathways associated with metabolic disorders." (PMID 40997104, 2025). "Chronic inflammation induced by proinflammatory cytokines like tumor necrosis factor-alpha (TNFα) during IDD is one of the major causes of metabolic disorder and dysfunction." (PMID 39552786, 2025). "High-fat diets (HFD) promote inflammatory markers such as IL-6, and TNF-α, and increase the risk of liver toxicity, leading to dysfunctional energy metabolism and causing metabolic disease and inflammation." (PMID 37231328, 2023). "Increases in specific inflammatory markers such as IL-6 and TNF-α, which can alter insulin sensitivity by triggering insulin signaling pathways, appear to be associated with metabolic disorders." (PMID 37152739, 2023). "It has been reported that the elevated levels of LPS and TNF-α, as well as the release of pro-inflammatory cytokines are important triggers of diseases associated with metabolic disorders." (PMID 36109620, 2022). "The degeneration of chondrocytes is a vital part of the progression of OA, and inflammatory elements such as IL-1β and TNF-α are regarded as the main cause of chondrocyte metabolic disorders." (PMID 35800437, 2022). "As a transcription factor, NF-κB plays a critical role in various inflammatory-associated metabolic diseases, and its activation induces the production of proinflammatory cytokines TNF-α, IL-1β and IL-6." (PMID 36139325, 2022). "Excessive TNF-α production causes systemic inflammation, which is eventually involved in the development of metabolic diseases." (PMID 35807067, 2022). "Inflammatory reactions are triggered by the production of pro-inflammatory cytokines such as TNF-α IL-1β, and IL-6 which are linked in the development of a number of metabolic diseases." (PMID 36552644, 2022). "Metabolic disorders associated with chronic diseases and inflammation were demonstrated by a high concentration of pro-inflammatory markers such as TNF-α, MCP-1 and IL-6, and a decrease in anti-inflammatory factors such as adiponectin." (PMID 36235241, 2022). "Next, we assessed levels of cytokines (TNF-α, IL-1β, and IL-6) that have been implicated in both metabolic disease and AD pathogenesis." (PMID 32993686, 2020). "Circulating serum levels of pro-inflammatory mediators, such as interleukin (IL)-1β, IL-6, tumor necrosis factor-α, C-reactive protein, and matrix metalloproteinases, are associated with both PD and lipoprotein disorders in elderly individuals." (PMID 33138320, 2020). "Further, highly increased TNF-α concentrations appear to be causally associated with the pathogenesis of diseases such as metabolic diseases, cardiovascular diseases, and OSAS." (PMID 32545460, 2020). "Chronic inflammation is an important pathogenic factor in metabolic diseases, and macrophages regulate inflammation by producing proinflammatory cytokines including tumor necrosis factor-alpha (TNF-α) and interleukin-1 beta (IL-1β)." (PMID 32443660, 2020). "As the adipose cells increase in number and size, they start to produce a series of compounds that regulate metabolism, such as peptides and cytokines IL-6 and TNF-α, associated with numerous metabolic disorders." (PMID 31861497, 2019). "The association of inflammation in metabolic disease can be seen as altered upregulated expression of the pro-inflammatory cytokine TNF-α in adipocytes of obese animals." (PMID 31597283, 2019). "Lipid-laden adipocytes secrete extremely high levels of metabolic disorder-associated factors, such as TNF-α, IL-6, resistin, and leptin." (PMID 31805752, 2019). "TNF-α and other cytokines have been described as biomarkers of cardiovascular risk in metabolic diseases." (PMID 27562094, 2016).
metabolic disorders (continued). "Some metabolic diseases that are simultaneously associated with aging can be easily identified and managed by assessing specific biomarkers (e.g., pro-inflammatory cytokines—tumor necrosis factor-alpha (TNF-α) and interleukin-6 (IL-6))." (PMID 39123632, 2024). "Likewise, leptin, a hormone involved in appetite regulation and energy balance and associated with a variety of metabolic diseases, and other pro-inflammatory cytokines such as IL-6 and TNF-α are essential in the pathophysiology of metabolic diseases." (PMID 39822427, 2024). "Inflammatory processes represent a chain of mechanisms triggering its manifestation; this complex metabolic disorder is linked with proinflammatory factor upregulation, including interleukin-1 and -6 elevated levels, tumor necrosis factor (TNF-alpha), and alpha-1-acid glycoprotein." (PMID 35328187, 2022). "Tumor necrosis factor (TNF) is a pro-inflammatory cytokine that controls the expression of numerous signaling pathways implicated in the progression of immunological reactions related to the development of various vascular and metabolic diseases." (PMID 35858838, 2022). "In adolescents with PCOS whose serum TNF-α is significantly elevated, dexamethasone may be used as an early treatment to reduce the risk of metabolic diseases and promote follicle growth." (PMID 33825169, 2021). "Metabolic disorders causing insulin resistance syndrome can be seen in gestational hypertension disorders including increased levels of plasminogen activator inhibitor −1, leptin, and tumor necrosis factor alpha." (PMID 24812607, 2014). "The prominence of TNF as a central regulator of adiposome proteome composition raises the intriguing possibility that vesicle cargo may serve not only as a readout of inflammatory signaling but also as a diagnostic or therapeutic target in metabolic disease." (PMID 40981199, 2025). "By suppressing pro-inflammatory cytokines such as tumor necrosis factor-alpha (TNF-α) and interleukins, and inhibiting nuclear factor-kappa B (NF-κB) signaling, tilianin helps mitigate chronic inflammation—a hallmark of autoimmune, cardiovascular, and metabolic diseases." (PMID 41254699, 2025). "Therefore, diminution of adiponectin (an anti-inflammatory adipokine) and exacerbation of TNF-α (a proinflammatory adipokine) in obese hypertensive subjects may be associated with severe metabolic disorders such as adverse cardiovascular or renal diseases." (PMID 29636702, 2018). "In addition to metabolic disorders, estrogen deficiency elevates low-grade systematic inflammation, with increased levels of proinflammatory cytokines, such as interleukin-1 (IL-1) and tumor necrosis factor-α (TNF-α) as well as prostaglandins." (PMID 29348767, 2017). "Among these, C-reactive protein (CRP), interleukin-6 (IL-6), and tumor necrosis factor-alpha (TNF-α) are well-recognized markers of systemic inflammation and have been associated with reduced muscle and brain function, and metabolic diseases in older adults." (PMID 40699540, 2025). "The effect on TNF-α was also evident from another metanalysis that evaluated the anti-inflammatory effect of CoQ10 on people affected by metabolic diseases." (PMID 40871615, 2025). "IL-6 and TNF-α levels are significantly higher in patients with metabolic disorders, including women with PCOS, also due to chronic inflammation." (PMID 40647668, 2025). "When TNF-α levels rise, as in chronic inflammatory and metabolic diseases, urinary Cys-C and ox-LDL levels typically increase, indicating underlying kidney dysfunction and oxidative stress." (PMID 40243674, 2025). "For instance, L. paraplantarum CRL 2051 reduces the production of pro-inflammatory cytokines such as TNF-α and IL-6 in a mouse model of metabolic disorders, highlighting its potential as an immunomodulator." (PMID 40284825, 2025).